CDK8 (cyclin dependent kinase 8)
Diseases named in the same sentence as CDK8 in open-access papers (continued):
Sharing a sentence is not in itself a finding about the gene and the disease.
cancer (continued). "It is worth noting that CDK8/19 inhibitors can increase cytotoxic activities of other drugs, and CDK8/19 is an important co-target in cancer therapy." (PMID 37376593, 2023). "Since Mediator kinases have been implicated in many tumor-promoting activities, the development of CDK8/19 inhibitors has become a burgeoning area in cancer therapeutics." (PMID 37378433, 2023). "The significance of alterations in mediator kinase components and cancer progression has spurned the development of specific CDK8/19 inhibitors (28, –, 30), several of which are in clinical trials for ER-positive breast cancers and acute myeloid leukemia." (PMID 37671866, 2023). "CDK8/19-based regulation was shown to be a therapeutic target in cancer cells and to affect certain immunogenic activities." (PMID 37376593, 2023). "Transcriptional reprogramming is critical for several biological and pathological processes that are suppressed by CDK8/19 inhibition, including embryonic development, cancer metastasis and drug resistance." (PMID 37378433, 2023). "The role of miR-567 in cancer proliferation has previously been described by other authors, and its role in regulating cyclin dependent kinase-8 (CDK-8) was recently proposed as a mechanism for inhibiting cell proliferation and inducing apoptosis." (PMID 35813211, 2022). "Cancer cells treated with CDK8 inhibitors responded with decreased cell viability and increased apoptosis." (PMID 36292630, 2022). "CDK8 was shown to maintain tumor dedifferentiation and embryonic stem cells pluripotency stage drugs resistance in several cancer disease models." (PMID 36292630, 2022). "In the future, it will be necessary to use drugs and combinations of these in cancers marked by Cdk8 and Cdkn2d expression." (PMID 36292630, 2022). "To determine if the essentiality of CDK8/10/12/13 is dependent on cancer type, we examined their gene effect score distributions across 26 different tissues of origin." (PMID 36577800, 2022). "The effects of CDK8 inhibition on anti-cancer immunity described so far are mostly limited to promoting anti-cancer NK cell activity." (PMID 36139513, 2022). "Mediator complex subunit 12 (MED12) has been reported as a potential biomarker of cancer and is a constituent of the CDK8 complex, which is involved in RNA pol II-mediated transcription." (PMID 36430260, 2022). "While CDK8/19 inhibition has promising perspectives for the cancer therapy, in vivo tests with several currently available inhibitors reported severe adverse effects in animals." (PMID 33444446, 2021). "As the effectiveness of traditional CDK8 inhibitors in the treatment of numerous cancers has yet to be confirmed, hence the need to elaborate new PROTACs for degrading the protein CDK8 became a driving force to overcome these shortcomings." (PMID 33802080, 2021). "In conclusion, these findings indicate that MED13 stabilization, through CDK8/19 inhibition with Senexin A, significantly sensitizes cancer cells to treatment with alkylating agents." (PMID 33444446, 2021). "Here, E3 ligase Skp2 was identified to mediate macroH2A1 ubiquitination and degradation, in turn promoting CDK8 gene and protein expression that contributed to cancer progression." (PMID 34203934, 2021). "Even though CDK inhibitors have been abundantly described, attempts of discovering selective CDK8 inhibitors have emerged as a promising strategy for cancer therapy as Pan-CDK inhibitor has shown narrow therapeutic window and potential risks." (PMID 32206448, 2020). "The scaffold substituent effects on the intrinsic inhibitory activity toward CDK8/CycC complex are addressed trying to present a novel outlook of CDK8/CycC Complex inhibitors with 4-phenylaminoquinoline scaffold in cancer therapy." (PMID 32206448, 2020). "Cyclin dependent kinase (CDK) 19 and its paralog CDK8 are part of its kinase domain and contribute to cancer progression in different cancer entities." (PMID 32752128, 2020).
cancer (continued). "Multiple studies identified CDK8 as being involved in a broad range of cancer types including colon, breast, ovarian, and gastric cancer, as well as acute myeloid leukemia." (PMID 32752128, 2020). "We note that a similar mechanism of Mediator hyperactivation via CDK8/19 inhibition has been reported in cancer cells." (PMID 32771524, 2020). "The role of CDK8 as an oncogene has been increasingly recognized and widely reported in several human cancers." (PMID 32596239, 2020). "CDK8 has also become a target of interest in other cancers such as acute myologenous leukemia (AML), melanoma, and prostate." (PMID 33291686, 2020). "CDK19 and its paralog CDK8 are known to promote different cancer-related pathways in several solid tumors, such as TGF-β/BMP-induced epithelial–mesenchymal-transition (EMT), and NFκB-mediated gene transcription." (PMID 32752128, 2020). "Structure-activity relationship (SAR) studies have revealed that steroidal analogs of cortistatin A to act as novel leads for further anti-cancer drug development mediated by inhibition of CDK8." (PMID 32635325, 2020). "Our findings identify CDK19 as a potential biomarker in HNSCC to predict recurrent disease and support recent developments to target CDK19 and its paralog CDK8 in advanced cancer." (PMID 32752128, 2020). "In a pan-cancer analysis, the RNA-Seq based expression level of CDK8 across all the 33 tumor entities publicly available at TCGA at the time of analysis for all 10,327 patients was obtained." (PMID 32596239, 2020). "To determine the expression pattern of CDK8 in human cancers, we performed a pan cancer analysis of CDK8 transcriptome profiles." (PMID 32596239, 2020). "Developing inhibitors targeting CDK8/CycC offers an exciting approach for treatment of human carcinomas." (PMID 32206448, 2020). "The role of the CKM, specifically Cdk8 upregulation, in the variety of cancers and conditions presented by studies thus far implies a positive regulatory capacity driven toward proliferation." (PMID 30621145, 2019). "Analysis of CDK8/CDK19/CCNC alterations identified several cancer subtypes where these genes were frequently altered." (PMID 31382571, 2019). "With this emerging picture, it seems unlikely that cancers where CDK8/19 inhibitors would have a beneficial impact will be defined as those that are growth-suppressed in vitro by CDK8/19 inhibition." (PMID 31382571, 2019). "CDK8/19 kinases, which mediate transcriptional reprogramming, have become an active target for cancer drug discovery." (PMID 31717492, 2019). "The development of CDK8 degraders not only provided a tool for regulating CDK8 protein levels in vivo, but also offered an effective strategy for treating cancer with CDK8 degraders." (PMID 31885879, 2019). "Further investigation of the oncogenic capacity of Cdk8 will allow a better understanding of the function of the CKM during cancer development." (PMID 30621145, 2019). "The observed association of the impact of CDK8 in cancers with low mutation burden is reasonable, since CDK8 regulates transcription and may be expected therefore to have a greater impact in those cancers that are driven primarily by changes in gene expression rather than mutations." (PMID 31382571, 2019). "In this section, we outline some of the concepts in targeting Cdk8 for cancer therapy and provide an example of repurposing an already established drug to target the non-transcriptional mode of action of cyclin C." (PMID 30621145, 2019). "An analysis of publicly available RNA-seq data from a range of human cancers suggests that CDK8 levels are highly correlated with the levels of members of the mTOR pathway." (PMID 31628323, 2019). "CDK8 and CDK19 Mediator kinases are transcriptional co-regulators implicated in several types of cancer." (PMID 31382571, 2019).
cancer (continued). "Examination of alterations in different cancers shows that CDK8, CDK19 and CCNC can be amplified or deleted either independently of each other or in combinations." (PMID 31382571, 2019). "CDK8 RNA expression was the most heterogeneous among tumors, with somewhat higher levels observed in cancers of the colon (including gene-amplified samples) and the stomach." (PMID 31382571, 2019). "We also analyzed a panel of putative cancer-related genes, including CDK8, MITF, SMAD7, KLF12, AG02, CDK14, and BCL-9, but only PTEN expression was shown to be significantly altered by miR-216a overexpression." (PMID 30061175, 2018). "Recently, several studies have explored the role of CDK8/19 in cancer by using small molecules that selectively inhibit CDK8/19." (PMID 29568371, 2018). "Of the 34 validated mutations that were significantly enriched in the lung metastases, 17 were predicted to impact protein function (SIFT41 and PolyPhen42), and four fell in cancer genes (CSF3R_Q250L, CDH11_A683S, GRIN2A_S752R, and CDK8_H235Y)." (PMID 30498242, 2018). "Transcription-regulating kinases CDK7, CDK9 and CDK8/19 have become actively pursued targets in cancer therapy, due in part to their effects on super-enhancers that develop during carcinogenesis and become essential for the survival of tumor cells." (PMID 28147342, 2017). "Western blot analyses of multiple cancer cell types revealed that most express both CDK8 and CDK19 protein." (PMID 28416637, 2017). "To facilitate this analysis, we identified a cancer cell line (SJSA) that is naturally depleted of CDK8 protein but retains CDK19." (PMID 28416637, 2017). "Activities of CDK8 and CDK19 have been implicated in sustained proliferation and viability of cancer cell lines, probably by modulation of various gene expression programs." (PMID 28422713, 2017). "Aberrations in transcriptional CDKs with direct modulation of target genes have also been described in human cancer such as CDK8, CDK9/cyclin T1, CDK10, and CDK11." (PMID 25914884, 2015). "Although its exact function is unknown, CDK8 helps keep cancers and embryonic stem cells in an undifferentiated state and stimulates cell proliferation via the serum response pathway." (PMID 40361480, 2025). "Encouragingly, two selective CDK8/19 inhibitors, RVU120 and BCD-115, are undergoing clinical trials for cancer therapy 21, 22, and the adverse effects of some CDK8/19 inhibitors have been revealed to be due to the off-target impacts and improper dose selection." (PMID 39781457, 2025). "Additionally, the phosphorylation of various transcription factors, such as Smads, STAT1, and NFκB, by CDK8 is frequently dysregulated in many other types of cancer." (PMID 40358161, 2025). "Inhibitors of CDK8/19, by suppressing the activity of CDK8/19, hold the potential to intervene in abnormal gene expression, regulate cell proliferation and survival, thus providing new therapeutic avenues and possibilities for cancer treatment." (PMID 38606172, 2024). "Several studies have determined the efficacy of CDK8 inhibitors in preclinical cancer models." (PMID 39574899, 2024). "Previous studies have positively correlated CDK8 and c-Myc expression in cancer." (PMID 39253786, 2024). "Despite the importance of CDK8 in regulating protein synthesis in MB, the mechanism by which dysregulation of protein synthesis contributes to cancer development and progression remains unclear." (PMID 39574899, 2024). "The investigation of combining CDK8 inhibitors with chemotherapy or radiotherapy is warranted in future research, as it potentially will enhance the therapeutic efficacy and long-term survival rate of cancer patients." (PMID 38606172, 2024). "Our data demonstrate that growth after recovery from repeated exposure to suspension stress is a direct contributor to metastasis and that inhibition of CDK8/19 Mediator kinase during such adaptation provides a therapeutic opportunity to prevent both local and distant metastasis in cancer." (PMID 38106208, 2023).
cancer (continued). "Collectively, our observations indicate that CDK8/19 inhibitors, including those currently in clinical trials for the treatment of various cancers, may prove useful for therapies to eliminate latently infected cells by suppressing HIV-1 expression." (PMID 37671866, 2023). "Anti‐cancer activity of CDK8/19 inhibitors has been somewhat limited, and it has been reported that there may be only a small therapeutic window, due to systemic toxicity." (PMID 36545778, 2023). "It was shown that ectopic expression of CDK8 inhibited proliferation in the KLE cancer cell line, and that it could even block growth of a mouse tumor model in vivo." (PMID 37718413, 2023). "Overexpression of CDK8 has been observed in various cancers." (PMID 35814446, 2022). "Cdk8 is a cycling-dependent kinase that is overexpressed mainly in many tumor tissues and that accelerates the growth and division process of cancer cells." (PMID 35391793, 2022). "More interestingly, CDK8 inhibitors may have the potential to be effective immune modulators for various cancers." (PMID 36342456, 2022). "CDK8 provides novel opportunities for the development of cancer therapeutics." (PMID 36342456, 2022). "For example, inhibitors of human Cdk8 have been extensively explored as potential cancer therapies." (PMID 34982775, 2022). "CDK8/19 inhibitors based on modified pyridines slowed the proliferation ofcolorectal cancer cells." (PMID 33959383, 2021). "The synthesis of CDK8 degraders will definitely help to clarify whether targeting CDK8 is an effective strategy for treating cancer." (PMID 33802080, 2021). "CDK8 is a mediator kinase and operates as a positive regulator of transcription, acting in the phosphorylation of polymerase II in specific networks, including cancer signaling pathways." (PMID 34444642, 2021). "However, CDK8 also functions in the pathogenesis of cancer as a mediator of damage-induced tumor-promoting paracrine activities." (PMID 34444642, 2021). "Consistent with previous data in other tumor types, our study indicated that CDK19 might contribute to HNSCC progression and aggressiveness, supporting recent developments to target CDK19 and its paralog CDK8 in advanced cancer." (PMID 32752128, 2020). "Recently, CDK19 and CDK8 emerged as promising potential therapeutic targets in cancer therapy." (PMID 32752128, 2020). "Therefore, CDK8/CycC complex represents as a cancer oncogene and it has become a potential target for developing CDK8/CycC modulators." (PMID 32206448, 2020). "Dysregulation of CDK8 (Cyclin-Dependent Kinase 8) and its regulatory partner CycC (Cyclin C), two subunits of the conserved Mediator (MED) complex, have been linked to diverse human diseases such as cancer." (PMID 32463833, 2020). "To identify other cancers where these novel drugs may provide benefit, we queried genomic and transcriptomic databases for potential impact of CDK8, CDK19, or their binding partner CCNC." (PMID 31382571, 2019). "The analysis was aimed at maximizing the number of cancer types that may be potentially affected by CDK8/19 and that would therefore warrant further investigation, rather than to draw definitive conclusions about the role of CDK8/19 in specific cancers." (PMID 31382571, 2019). "Stratification by TMB didn’t change the nature of CDK8 correlations in other cancer types." (PMID 31382571, 2019). "In addition to playing role in cancer cells, Cdk8 demonstrates a positive regulatory role in normal cell types during differing conditions." (PMID 30621145, 2019). "CDK8 has attracted much attention over the last years as potential target for cancer therapy." (PMID 31628323, 2019).
cancer (continued). "The ability of CDK8/19 inhibitors to suppress metastatic growth and to prevent the development of therapy resistance suggests a potentially transformative potential for combinations of these inhibitors with various cancer therapeutic regimens." (PMID 31717492, 2019). "And a number of inhibitors targeting Cdk8 have been developed to treat cancers." (PMID 31552016, 2019). "Since many tumor cells are proliferating in hypoxic conditions, it could be suggested that the upregulation of Cdk8 in cancer cells is preceded by the activation of HIF1α target genes by the CKM." (PMID 30621145, 2019). "CDK8 is essential for β-catenin-dependent oncogenesis and progression in all kinds of cancers." (PMID 30524203, 2018). "Modulation of response to genotoxic stress has been postulated as one of the therapeutically relevant mechanisms of action for CDK8 inhibitors, which may increase efficacy of cancer chemotherapy." (PMID 28422713, 2017). "The ability to prevent the development of estrogen independence, a major clinical problem in hormone therapy of ER-positive cancers, may offer the greatest therapeutic benefit in the future clinical use of CDK8/19 inhibitors." (PMID 28147342, 2017). "In an effort to better delineate CDK19-specific roles from potential redundant functions of CDK8, we screened cancer cell lines to assess whether any might serve as a useful “model system” to study CDK19." (PMID 28416637, 2017). "The exact role of CDK8 in the process of immune-evasion of cancer cells is still unknown, however it may be partially related to the STAT1 S727 dependent repression of NK-cells cytotoxicity." (PMID 28422713, 2017). "This is particularly true in cancer, where CDK8 may function not only as an oncogene, but also as a tumor-suppressor depending on the cellular context." (PMID 27935476, 2016). "However, the small molecules they describe will be important probes in research to study exactly how CDK8/19 regulate gene activity in both healthy cells and cancers." (PMID 27935476, 2016). "Therefore, the roles of CDK8/19 inhibitors in cancer chemotherapy and immunotherapy may require particular attention to the antitumor activities of macrophages." (PMID 37376593, 2023). "Firstly, ChIP-Seq for RNA polymerase II revealed that overall RNA polymerase II binding and distribution were unchanged after CDK8/19 deletion, indicating that, in contrast to cancer cells, loss of CDK8/19 does not affect global gene regulation in normal intestine." (PMID 36006697, 2022). "Thus, CDK8 clearly has divergent roles in different cancer entities." (PMID 34689158, 2021). "Thus, targeting CDK8 in cancer patients could prevent tumor progression and immune evasion while enhancing NK-cell cytotoxicity." (PMID 34689158, 2021). "Thus, CDK8 is a potent candidate target to enhance cancer radiotherapy." (PMID 32596239, 2020). "Thus cancer cell oncogenic SEs may be sensitive to perturbation, either when hyperactivated, as in the case of CDK8 inhibition, or when inhibited, as in the case of BRD4 inhibition." (PMID 32771524, 2020). "Therefore, combining with Treg inhibition might improve the therapeutic effect of Cdk8/Cdk19 inhibitors in cancer therapy." (PMID 31552016, 2019). "On the other hand, potential target cancers could be identified through informatic analysis of clinical data, which may reveal tumor types where CDK8/19 or their binding partner Cyclin C (CCNC) would be amplified or overexpressed or where CDK8/19 expression would be associated with bad prognosis." (PMID 31382571, 2019). "CDK8 has been linked to the KRAS, Notch, gamma interferon (IFN-γ), and Wnt/β-catenin signaling pathways in mammalian cells (22, –, 25), and a growing number of studies link the Mediator kinase module to developmental diseases and specific types of cancer (26, –, 34)." (PMID 28416637, 2017).